ZNF703 (zinc finger protein 703)
Diseases named in the same sentence as ZNF703 in open-access papers (continued):
Sharing a sentence is not in itself a finding about the gene and the disease.
glioma (1 paper, 2024). A benign or malignant brain and spinal cord tumor that arises from glial cells (astrocytes, oligodendrocytes, ependymal cells). "Through pairwise group comparisons and a subsequent intersection of gene lists, we identified two genes, LRIG1 and ZNF703, exhibiting higher 5hmC levels in glioma patients/tissues when compared to healthy individuals/normal brain tissue." (PMID 38790164, 2024). "In our current study, we identified genes LRIG1 and ZNF703 with 5hmC gene levels higher in both the cfDNA and gDNA of glioma patients." (PMID 38790164, 2024). "The intersection of gene lists derived from these comparative analyses unveiled LRIG1 and ZNF703 as the two genes with elevated 5hmC levels in both the cfDNA of glioma patients and gDNA of glioma tissue compared to their respective controls." (PMID 38790164, 2024). "Therefore, we could examine the expression of genes LRIG1 and ZNF703 in the glioma and normal tissue samples." (PMID 38790164, 2024). "The gene ZNF703 exhibited the average mean logFC of 1.95 in the glioma samples and 1.61 in the normal samples, without significant difference (p-value 0.10)." (PMID 38790164, 2024). "The intersection of gene lists that showed positive differences in 5hmC levels between glioma and normal/healthy samples resulted in two promising candidate genes: leucine-rich repeats and immunoglobulin-like domains protein 1 (LRIG1) and zinc finger protein 703 (ZNF703)." (PMID 38790164, 2024).
laryngeal carcinoma (1 paper, 2015). Carcinoma that arises from the laryngeal epithelium. "ZNF703 overexpression was correlated with tumor position (laryngeal carcinoma) and recurrence (all P < 0.05)." (PMID 26063961, 2015).
larynx cancer (1 paper, 2015). A primary or metastatic malignant neoplasm involving the larynx. "Furthermore, ZNF703 overexpression was observed more frequently in larynx cancer and was correlated with higher risk of recurrence." (PMID 26063961, 2015).
leiomyoma (1 paper, 2023). A well-circumscribed benign smooth muscle neoplasm characterized by the presence of spindle cells with cigar-shaped nuclei, interlacing fascicles, and a whorled pattern. "For comparison of differential expression of genes in leiomyomas, there was a significant race/ethnicity correlation in expression for TNFRSF19, IRS4, PLEKHG4B, PGR, KRT17, CCDC177, MYO5B, and ZNF703." (PMID 37686244, 2023).
tumor (30 papers, 2013 to 2024). "We also investigated phosphorylation of the Akt1 protein as an indicator of the Akt1/mTOR pathway activation in 43 tumor samples in association with ZNF703 expression." (PMID 27650486, 2016). "Statistical results demonstrated that the expression of ZNF703 was strongly linked to tumor location (P=0.002), pathological grading (P=0.024), depth of invasion (P=0.002), distant metastasis (P=0." (PMID 27764785, 2016). "High expression of ZNF703 luminal B tumor patients is associated with poor clinical outcome." (PMID 37514116, 2023). "In luminal tumours, ZNF703 amplification and overexpression is associated with a poor prognosis." (PMID 35459982, 2022). "High expressionof ZNF703 was significantly associated withmore tumor number, larger tumor size, poor tumor differentiation, tumor vascular invasion, loss of tumor encapsulation, morelymph node metastasisand advanced tumor-node metastasis (TNM) stage." (PMID 32269215, 2020). "Interestingly, further studies reported that patients with higher N stage and high risk of tumor relapse and death had a higher level of ZNF703 expression (P < 0.05)." (PMID 26063961, 2015). "The expression of several race-associated genes was also dependent on the MED12 mutation status of the tumor, being higher (FRAT2, TNFRSF19, ACP7, IRS4, PLEKHG4B, KRT17, SLN, and ZNF703) or lower (CAV2) in the mutated specimens compared with wild-type tumors." (PMID 37686244, 2023). "Collectively, these compelling results underscore the substantial impact of tumor cell-expressed ZNF703 on tumor immunity." (PMID 37821882, 2023). "The abnormal expression of ZNF703 affects the biological behavior of tumor cells and the prognosis of patients." (PMID 37821882, 2023). "Of note, ZNF703 expression was significantly upregulated in tumor tissues as compared to normal tissues in TCGA COAD cohort, and verified in GSE32323, GSE44076, GSE89076, and GSE113513." (PMID 37821882, 2023). "In our investigation, ZNF703 exhibited elevated expression levels within tumor tissues, concurrently demonstrating a favorable prognostic association at the mRNA level." (PMID 37821882, 2023). "ZNF703 overexpression increases cell proliferation, stimulates tumor migration/invasion, and is involved in endocrine and chemoresistance in luminal B BCs." (PMID 37514116, 2023). "As a fifth molecules, lncRNA LSINCT5 was aberrantly upregulated in OSCC and drove tumor progression by decreasing miR-185-5p and increasing ZNF703 levels; ZNF703 has been characterized to be an oncogene in OSCC and a target of miR-185-5p." (PMID 36287119, 2022). "We also examined ZNF703 expression in the tumor tissue block of 76 TNBC patients by immunohistochemistry." (PMID 35236318, 2022). "Five of the 38 cases (13.2%) also had mean ZNF703 CN ≥ 6 and of these, one tumour was histopathological grade 2 and four were grade 3." (PMID 35459982, 2022). "Zinc Finger Protein 703 (ZNF703) has been reported to be abnormally expressed in many different malignancies and its aberrant expression is involved in tumor progression." (PMID 32269215, 2020). "Several recent studies reported that the aberrant expression of ZNF703 is involved in tumor progression." (PMID 32269215, 2020). "We demonstrated that the overexpression of ZNF703 in human HCC tissue is correlated with tumor metastasis and recurrence, it is also related with the prognosis and survival rate of patients." (PMID 32269215, 2020). "Recent studies confirmed that the expression of ZNF703 promoted tumor progression and was abnormally increased in breast, lung, and gastric cancers." (PMID 33246486, 2020). "Compared with the control group, ZNF703 overexpressed mice resulted in a significant increase of tumor size while the ZNF703 inhibited mice presented tumors with small size." (PMID 27764785, 2016). "High expression of ZNF703 was related to tumor location (P=0.002), pathological grading (P=0.024), depth of invasion (P=0.002), distant metastasis (P=0." (PMID 27764785, 2016).
tumor (continued). "In our study group we observed ZNF703 overexpression in 64.1% of NSCLC tumor samples harboring ZNF703 amplification." (PMID 27650486, 2016). "The average increase in ZNF703 mRNA in the tumor tissues was 55% when compared with corresponding normal tissues." (PMID 27650486, 2016). "The overexpression rate of ZNF703 protein was 48.6% in HNSCC tumor cells, it was significantly higher than that of the adjacent noncancerous squamous epithelium cells (48.6% versus 11.6%, P < 0.001)." (PMID 26063961, 2015). "According to The Cancer Genome Atlas (TCGA) database, which included 4000 cases and more than 20 tumor types, ZNF703 is one of the most frequently altered genes in the pan-cancer group." (PMID 26063961, 2015). "Furthermore, the gains on 8p11 encompassing FGFR1 and ZNF703 is the second most common hotspot in our analysis (#2), which agrees with previous tumor-related literature." (PMID 38473323, 2024). "Additionally, we performed IHC analysis on tissue sections from 56 CRC patients to delve into the relationship between ZNF703 and tumor immunity at the protein level." (PMID 37821882, 2023). "ZNF703 might also play a role in tumor metastasis by promoting EMT through the repression of E-cadherin expression." (PMID 37514116, 2023). "ZNF703 might play a role in tumor metastasis by promoting epithelial-mesenchymal transition (EMT) through the repression of E-cadherin expression." (PMID 37514116, 2023). "Targeting ZNF703 contributed to the anti-tumor effects in TNBC cells through G1-phase arrest." (PMID 35236318, 2022). "In vivo experiments also proved that ZNF703 overexpression promoted tumor formation and growth." (PMID 33246486, 2020). "Moreover, enhancers of migration and angiogenesis such as GPNMB, PTGS2, CD274, and ZNF703 were significantly downregulated suggesting suppression of tumor malignancy." (PMID 31842391, 2019). "In addition, 11 tumor-specific exonic variants were identified in six genes spanning the 8p11-p12 genomic region (RAB11FIP1, GPR124, ADAM2, LSM1, TACC1, ZNF703)." (PMID 29844878, 2018). "Taken together, ZNF703 could potently facilitate tumor growth and metastasis in many respects throughout the progression of CCA." (PMID 27764785, 2016). "ZNF703 can potently facilitate tumor growth and metastasis in many respects throughout the progression of CCA, which may act as an oncogene in CCA and can be considered as a novel potential therapeutic target." (PMID 27764785, 2016). "Our results show that ZNF703 is up‐regulated in 63.4% of NSCLC tumor samples." (PMID 27650486, 2016). "Our data show that ZNF703 may contribute to tumor development in NSCLC by activating the Akt/mTOR pathway." (PMID 27650486, 2016). "Moreover, the high expression of ZNF703 was related to tumor location (P=0.002), pathological grading (P=0.024), depth of invasion (P=0.002), distant metastasis (P=0." (PMID 27764785, 2016). "Overexpression of ZNF703 increases genome instability and contributes to tumor aggressiveness." (PMID 23991038, 2013). "Interestingly, mimicking endogenous estrogen levels, low-dose tamoxifen stimulated the growth of tumor cells upon ZNF703 overexpression." (PMID 23991038, 2013). "Moreover, we identified ZNF703 as a promising target for tumor immunity." (PMID 37821882, 2023). "The distribution of Tumor Mutation Burden (TMB) was also similar in cancers with ZNF703 amplifications compared with ZNF703 non-amplified cancers, besides the subset with TMB above 13 where non-amplified tumors were more commonly observed, in the METABRIC cohort." (PMID 32987805, 2020). "After correction for age, tumor size, stage and grade, ER/PR/HER2 status and 3-gene classifier subtype, the loss of WRN (p=0.053; HR 1.2), DUSP26 (p=0.022; HR 1.3), UNC5D (p=0.026; HR 1.3), ZNF703 (p=0.026; HR 1.3) and FGFR1 (p=0.002; HR 1.5) still predicted worse DFS." (PMID 29682206, 2018).
tumor (continued). "Thus, ZNF703 may represent an important downstream effector of SPRY4-IT1 that potentially mediates the effects of this lncRNA on tumor growth." (PMID 25742952, 2015). "Tumor sequencing revealed LOH in CHEK2 and PALB2, as well as CCND1,FGFR1, GPR124, ZNF217, ZNF703, and PTPN1 amplifications." (PMID 38091153, 2024). "It has been shown that ZNF703 induces EMT through repressing E-cadherin expression and stimulates tumor migration and invasion in breast cancer." (PMID 32269215, 2020). "This phenomenon of co-localising chr8:ZNF703/FGFR1 and chr11:CCND1 amplicons tends to be seen in ER-positive tumours, among patients diagnosed at an older age." (PMID 30252041, 2018). "Moreover, Reynisdottir and his colleagues had reported that ZNF703 displayed in tamoxifen resistance induced by activation of the Akt/mTOR signaling pathway and downregulation of estrogen receptor alpha, providing a potential mechanism of its action in tumor growth." (PMID 27764785, 2016). "Notably, immumohistochemical staining (IHC) of our central cohort demonstrated ZNF703 was correlated with CD8 + T cell infiltration, and potentially be a promising target for tumor immunity." (PMID 37821882, 2023). "Moreover, the tumor tissues of PEA15, p-PEA15 (Ser116) and p-PEA15 (Ser104) were stained more deeply in the ZNF703-overexpressing group than in the control group." (PMID 33246486, 2020). "We observed ZNF703 overexpression in a high fraction of tumor tissues (63.4%) compared to the noncancerous tissue samples." (PMID 27650486, 2016). "In five of the tumor tissues and 10 of the noncancerous tissues ZNF703 mRNA was not present." (PMID 27650486, 2016). "To further investigate these phenomena, we examined the expression of ZNF703 mRNAs and proteins in 20 HCC tumor specimens and the adjacent nontumor tissues, we found that ZNF703 mRNA and protein expressions were apparently higher in HCC samples compared with those in adjacent nontumor tissues." (PMID 32269215, 2020).
cancer (22 papers, 2012 to 2024). A tumor composed of atypical neoplastic, often pleomorphic cells that invade other tissues. "ZNF703 mRNA over-expression correlates better with gene amplification of the gene in luminal B cancers and was associated with worse overall survival." (PMID 32987805, 2020). "The ZNF703 gene has been identified as the driver of the 8p11‐12 region and its amplification or overexpression has been associated with several types of cancers." (PMID 27650486, 2016). "Starting from the discovery of the oncogene ZNF703 as a lncMB2 target gene, we were able to demonstrate a role for the lncRNA in promoting cell migration and invasion, processes underlying cancer metastasis." (PMID 34359754, 2021). "ZNF703 overexpression facilitates tumorigenesis, metastatic invasion, and predicts poor prognosis in luminal B BCs but also in other advanced cancers." (PMID 37514116, 2023). "ZNF703 is a transcriptional corepressor that regulates many genes involved in multiple facets of the cancer phenotype, including proliferation, invasion, and regulation of stem cells." (PMID 37514116, 2023). "ZNF703 is a transcriptional corepressor that regulates many genes involved in multiple aspects of the cancer phenotype, such as proliferation, invasion, and altered balance of stem cells." (PMID 37514116, 2023). "And there is one study reported that mRNA and protein levels of ZNF703 were upregulated in CRC tissues than normal mucosal tissues, and patients with high protein levels of ZNF703 exhibited poor cancer-specific survival." (PMID 37821882, 2023). "This also applies to supporting the activities of zinc finger-containing transcription factors, some of which, such as ZEB1 and ZNF703, have been found to be human oncogenes responsible for pro-invasive and poorly differentiated stem-like cancer phenotype." (PMID 34572758, 2021). "Several studies have shown that the expression of ZNF703 was increased in malignant tumors and promoted the development of tumors." (PMID 33246486, 2020). "In contrast, inhibition of ZNF703 induced cancer cell cycle arrest in the G0/G1 phase (all P < 0.05), which was confirmed by the reduction of cyclin D1 protein." (PMID 33246486, 2020). "Regarding clinicopathologic characteristics, ER+/HER2-/high proliferation cancers were over-represented in the ZNF703-amplified group (as representative of the presence of the whole amplicon)." (PMID 32987805, 2020). "It's obvious to see from IHC staining that ZNF703 was overexpressed in CCA tissues compared to the matched para-carcinoma ones, with subcellular localizations mainly in the nucleus and partly in the cytoplasm or membrane." (PMID 27764785, 2016). "ASO-based inhibition of ZNF703 may be useful in the treatment of luminal B BCs as well as other advanced cancers either as a monotherapy or in combination with other therapies." (PMID 37514116, 2023). "Thus, ZNF703 overexpression facilitates tumorigenesis, metastatic invasion, and predicts poor prognosis in various advanced cancers." (PMID 37514116, 2023). "Scientists have explored about ZNF703 (Zinc finger 703) in cancer fields." (PMID 35236318, 2022). "In addition, immunohistochemical staining of the tissue showed that compared with the control group, the color of the Ki-67 staining of cancer cells overexpressing ZNF703 was darker." (PMID 33246486, 2020). "Furthermore, in the ZNF703-overexpression group, the proliferation and invasion ability of cancer cells increased, and the cancer cells showed nodular growth." (PMID 33246486, 2020). "We also explored the impact of ZNF703 expression on cancer migration through wound-healing method." (PMID 27764785, 2016). "ZNF703 is one of the oncogenic transcription factors that regulates the expression of multiple genes involved in transcription modulation, stem cell regulation, cancer proliferation and invasion." (PMID 27764785, 2016). "ZNF703 inhibition may be a potential targeted treatment for such advanced cancers." (PMID 37514116, 2023).
cancer (continued). "Researchers had identified ZNF703 as a cofactor of a nuclear complex covering DCAF7, PHB2 and NCOR2 through mass spectrometry and pointed out that ZNF703 expression could result in the activation of stem cell-related gene expression leading to an increase in cancer stem cells." (PMID 27764785, 2016). "Next, we addressed the function of lncMB2 and lncMB1. lncMB2 is a predominantly nuclear transcript, whose proximal genes ZNF703 and ADGRA2, mapping about 360 Kb and 460 Kb apart from lncMB2 locus (AC091182.1), respectively, are both related to cancer." (PMID 34359754, 2021). "ChIP-Seq identified multiple regulatory targets of ZNF703, of which ZNF703 directly binds to the enhancer region of PEA15 to promote the transcription of PEA15 and thereby promoted the proliferation of cancer cells." (PMID 33246486, 2020). "In general, ZNF703 may act as a transcriptional repressor and affect target genes which mediate various aspects of cancer pathophysiology, such as epithelial-mesenchymal transition, adhesion, motility, proliferation and cancer stem cell renewal, CDH1, cadherin-1, CTTND1, p120-catenin and TGFBR2." (PMID 27764785, 2016). "These potential alternative driver alterations were found to affect known cancer genes, including amplification of PIK3CA or MYC, and likely driver genes mapping to the 8p11-p12 amplicon, including ZNF703, RAB11FIP1, LSM1, PPAPDC1B, WHSC1L1 and FGFR1." (PMID 25994018, 2015). "Although there is still no direct report about the pathogenic mechanism of ZNF703 in HNSCC, reports in other cancer types may help to understand its mechanism." (PMID 26063961, 2015). "Cancers with positive ER, negative PR and of the luminal B phenotype in the PAM50 classification were also over-represented in the ZNF703-amplified group." (PMID 32987805, 2020).
ZNF703 also shares sentences with these, for which no sentence is quoted: adenocarcinoma (2 papers); lymph node metastases (2); brain tumors (1); clear renal cell carcinoma (1); coloboma (1); endometrium (1); invasive breast carcinoma (1); liver cancer (1); medullary thyroid carcinoma (1); non-small cell lung carcinoma (1); oral cancer (1); oral squamous cell carcinoma (1); papillary thyroid carcinoma (1); prostate carcinoma (1); squamous cell carcinomas of the lung (1); thyroid cancer (1).